BRAF (B-Raf proto-oncogene, serine/threonine kinase)
Diseases named in the same sentence as BRAF in open-access papers (continued):
Sharing a sentence is not in itself a finding about the gene and the disease.
metastatic melanoma (continued). "Therefore, it is an effective therapeutic option in patients with unresectable or metastatic melanoma, with a BRAF V600E or V600K mutation." (PMID 31058077, 2019). "Based on the results of the phase III CheckMate 037 trial, nivolumab received its first FDA-approved indication in December 2014 for the treatment of unresectable/metastatic melanoma after failure of ipilimumab and, if BRAF V600 mutation positive, a BRAF inhibitor." (PMID 31640266, 2019). "In late 2014, both nivolumab and pembrolizumab received their first FDA-approved indications for use in unresectable or metastatic melanoma in patients with history of disease progression following ipilimumab and, if BRAF V600 mutation positive, BRAF inhibition." (PMID 31640266, 2019). "Although a high discordance rate of the BRAF p.V600E mutation has been reported in 8 (44%) of 18 paired primary and metastatic melanoma specimens, BRAF and NRAS mutations are generally highly concordant with variation of discordance rates depending on the metastatic sites in larger cohort studies." (PMID 31277584, 2019). "In the present study we enrolled a total of 11 BRAF-mutated metastatic melanoma patients." (PMID 31557826, 2019). "Currently, there are three BRAF–MEK inhibition combination therapies approved for first-line treatment of metastatic melanoma with BRAF V600 activating mutations, including: Vemurafenib plus cobimetinib, dabrafenib plus trametinib, and encorafenib plus binimetinib." (PMID 31817473, 2019). "This drug has proved to improve overall survival in adult patients with unresectable or metastatic melanoma with a BRAF V600 mutation and could be useful for the treatment of specific T-ALL subsets." (PMID 31655559, 2019). "Whether the expression of the BRAF V600E mutation could define distinct molecular phenotypes for the two groups of mutation-positive metastatic melanomas was also explored." (PMID 31835364, 2019). "The BRAF mutational status was studied in 56 tumor samples from metastatic melanoma patients." (PMID 31835364, 2019). "This platform allows the determination of BRAF mutational status in less than two hours, including sample preparation, and has been proven suitable for routine molecular diagnosis of patients with metastatic melanoma." (PMID 30181812, 2018). "Nivolumab (Opdivo, Bristol-Myers Squibb), the fully human IgG4 anti-PD-1 antibody, was approved by the FDA in December 2014 for unresectable or metastatic melanoma that progressed after ipilimumab therapy and for patients with positive BRAF V600 mutation who failed treatment with BRAF inhibitors." (PMID 30519261, 2018). "However, due to drug resistance, trametinib has only been approved by the FDA, in combination with dabrafenib, for the treatment of BRAF-mutated metastatic melanoma and advanced non-small cell lung cancer." (PMID 30185207, 2018). "Consistently, eNAMPT levels are elevated in 113 patients with BRAF-mutated metastatic melanoma compared to 50 with localized disease or to 38 healthy donors, showing a direct correlation with markers of tumor burden, such as LDH, or aggressive disease (such as PD-L1)." (PMID 29721178, 2018). "More recently, the striking clinico-pathological features of cSCCs that complicate treatment of metastatic melanoma with inhibitors targeting BRAF mutations (BRAFi) has prompted speculation concerning a pathogenic role for oncogenic viruses." (PMID 30154763, 2018). "We aimed to assess whether rapid determination of BRAF mutational status had an effect on the overall care of patients with metastatic melanoma." (PMID 30181812, 2018). "All patients had metastatic melanoma with V600E BRAF mutations." (PMID 30154763, 2018). "These preliminary data support TIL therapy with lifileucel as an efficacious and well tolerated therapeutic option for patient with metastatic melanoma who have failed multiple lines of prior therapies including checkpoint inhibitors and BRAF/MEK inhibitors (if BRAF mutated)." (PMID 30400822, 2018).
metastatic melanoma (continued). "A total of 53 patients with BRAF V600-mutated metastatic melanoma were enrolled onto this trial." (PMID 30053905, 2018). "In addition to BRAF mutations, metastatic melanoma frequently harbors activating NRAS mutations (15%–28%) for which MEK inhibitor therapy has shown early clinical activity." (PMID 28147313, 2017). "Therefore, the combination of BRAF and MEK inhibitors is now the current standard treatment for BRAF mutated metastatic melanoma." (PMID 29179510, 2017). "In patients with BRAFV600 mutated unresectable stage IIIc or metastatic melanoma, molecular targeted therapy with combined BRAF/MEK-inhibitor vemurafenib plus cobimetinib has shown a significantly improved progression-free survival and overall survival compared to treatment with vemurafenib alone." (PMID 28915798, 2017). "Based on these clinical trials revealing the clinical benefit of the combination the FDA approved in November 2015 vemurafenib plus cobimetinib as well as dabrafenib plus trametinib for the treatment of patients with unresectable or metastatic melanoma with BRAF V600E or V600K mutations." (PMID 28915798, 2017). "For instance, the promising results from clinical trials involving triple combination therapy with BRAF-MEK inhibitors and anti-PD-L1 antibodies in BRAF-mutated metastatic melanoma may take advantage of this pro-inflammatory component." (PMID 29064427, 2017). "Fifty-nine samples from patients with metastatic melanoma were assessed for BRAF mutations using IdyllaTM, high resolution amplicon melting (HRM), real-time allele specific amplification (RT-ASA), next generation sequencing (NGS) and immunohistochemistry (IHC)." (PMID 27111917, 2016). "For example, a rare activating BRAF mutation (p.L597R) was identified in an aggressive metastatic melanoma using whole genome sequencing that had previously been designated as “wild-type” for BRAF p.V600E/K mutations and several common KIT mutations using targeted sequencing." (PMID 27245685, 2016). "Response to anti-BRAF therapies in patients with metastatic melanoma bearing complex mutations or single mutation other than V600 have already been described in the literature but only p.V600 mutations are officially recognized as response biomarkers for the use of vemurafenib and dabrafenib." (PMID 27111917, 2016). "BRAF inhibitors may be useful in the treatment of metastatic melanoma in patients with BRAF mutations." (PMID 27124046, 2016). "One of the treatments for metastatic melanoma is based on BRAF V600E mutation gene." (PMID 26884744, 2016). "Approximately 50% of metastatic melanoma patients harbor BRAF mutations." (PMID 27447748, 2016). "BRAF mutations are found in approximately 50% of metastatic melanomas with V600E (c.1799T>A; p.Val600Glu), V600K (c.1798_1799delinsAA; p.Val600Lys), V600R (c.1798_1799delinsAG; p.Val600Arg) and V600M (c.1798G>A; p.Val600Met) in 79%, 12%, 5% and 4% frequencies respectively." (PMID 27111917, 2016). "The BRAF p.L597R mutation was demonstrated to be responsive to MEK inhibitors in metastatic melanomas, suggesting that with more comprehensive testing the patient in question may have benefitted from this treatment option." (PMID 27245685, 2016). "Vemurafenib and dabrafenib are BRAF-targeting TKIs, approved in BRAF-mutated metastatic melanoma." (PMID 27200298, 2016). "Approximately two-thirds of those patients (those with the BRAF mutation) might benefit from targeted therapy with BRAF inhibitors, which have been developed for treatment of metastatic melanoma." (PMID 25712893, 2015). "BRAF V600E is the most common somatic mutation seen in patients with metastatic melanoma." (PMID 26824010, 2015). "Based on these data, trametinib was approved by FDA as monotherapy for use in patients with V600E or V600K BRAF mutated unresectable or metastatic melanoma in May 2013." (PMID 25915534, 2015).
metastatic melanoma (continued). "Since vemurafenib is much more effective in the BRAF-mutated metastatic melanoma lesions than cytotoxic drugs, the clinical effect might have been more noticeable in the leptomeninges." (PMID 25962795, 2015). "The recent evidence of BRAF oncogenic mutation may offer new therapeutic options with vemurafenib and anti-BRAF targeted therapy approved for the treatment of metastatic melanoma with V600 mutation." (PMID 25789184, 2015). "A phase III clinical trial of vemurafenib compared to the standard therapy dacarbazine in previously untreated metastatic melanoma with known BRAF V600E mutation demonstrated an increase in overall survival of 20%, and a reduction of 63% in the risk of death in the vemurafenib group." (PMID 25785246, 2015). "Interestingly, a phase II study of dabrafenib demonstrated that it also has a clinically meaningful clinical activity in the brain in patients with metastatic melanoma harboring a BRAF V600E mutation, similar to its activity in the extracranial organs." (PMID 25962795, 2015). "Taken together, our findings support the concept that triple therapy directed against BRAF/MEK/ErbB3 may be able to provide durable control of BRAF mutated metastatic melanoma." (PMID 26208478, 2015). "Importantly, these EMT-associated signaling pathways also have roles in conferring resistance to inhibitors of BRAF/MEK, hindering therapeutic outcomes in patients with metastatic melanoma driven by BRAF mutations." (PMID 25763355, 2015). "Dabrafenib is an oral therapy approved for use in BRAF V600E-mutated metastatic melanoma." (PMID 25089220, 2014). "Over 50% of metastatic melanomas harbor the BRAF(V600E) point mutation (T1799A)." (PMID 24732172, 2014). "Dabrafenib is indicatedfor use in BRAF V600E-mutated metastatic melanoma." (PMID 25089220, 2014). "A BRAFV600E mutation specific antibody is available and a recent small study suggested that vemurafenib (a BRAF inhibitor with significant activity against BRAF mutated metastatic melanoma) may improve outcomes in adults with recurrent BRAFV600E mutated PXA." (PMID 24716189, 2014). "Several treatments for metastatic melanoma with a mutation in the BRAF gene have been approved." (PMID 25198196, 2014). "In an open label phase I/II trial, combination BRAF and MEK inhibition with dabrafenib and trametinib (respectively) improved progression free survival from 5.8 months with dabrafenib monotherapy to 9.4 months with combination therapy in metastatic melanoma patients with BRAF V600 mutation." (PMID 24499550, 2013). "In addition, only patients whose tumors harbor the V600 mutation can benefit from vemurafenib, hence its approval only for the treatment of patients with unresectable or metastatic melanoma with BRAF V600E mutation." (PMID 23738073, 2013). "Indeed, both ipilimumab (a fully human monoclonal antibody that blocks CTLA-4 to promote antitumor immunity) and vemurafenib (a potent inhibitor of mutated V600E BRAF) have been recently approved in Europe and the US for the treatment of metastatic melanoma." (PMID 23402397, 2013). "It is being evaluated by FDA for the treatment of metastatic melanoma with BRAF V600 mutation." (PMID 24238212, 2013). "Interestingly, we identified V600K BRAF mutation as a prognostic factor associated with more aggressive behavior in metastatic melanoma." (PMID 22039425, 2011). "Dabrafenib is a kinase inhibitor used for treating patients with unresectable or metastatic melanoma, metastatic non‐small cell lung cancer, locally advanced or metastatic anaplastic thyroid cancer, pediatric low‐grade glioma, and other solid tumors harboring specific BRAF mutations." (PMID 40237399, 2025). "Further studies have shown that in patients with BRAF-mutated metastatic melanoma, the combination of the BRAF inhibitor Dabrafenib and the MEK inhibitor Trametinib may be an effective therapeutic modality, demonstrating impressive remission rates and survival benefits." (PMID 40641936, 2025).
metastatic melanoma (continued). "Furthermore, in a study evaluating the prognostic significance of serum LDH as a function of BRAF mutation status, it was shown that elevated serum LDH levels are associated with poor outcomes in patients with metastatic melanoma in both BRAF mutant and BRAF wild-type cases." (PMID 39272837, 2024). "New drugs and drug combinations are being developed to improve the treatment of metastatic melanoma, as researchers have found secondary resistance to existing treatments like tyrosine kinase inhibitors (RTKs), especially those directed at activating BRAF mutations, CTLA4, and PD1 inhibitors." (PMID 39280375, 2024). "The working hypothesis of this study, therefore, is that the use of BRAF inhibitors in patients with metastatic melanoma presenting a BRAF mutation provokes the reinduction of acquired immunity against the tumour and that changes in immunological blood biomarkers indicate this re-establishment." (PMID 35203494, 2022). "In addition, metastatic melanoma is easily resistant to BRAF inhibitors, and serine synthesis may be the cause of drug resistance." (PMID 34976824, 2021). "If CT-based radiomics could predict BRAF mutation status with a high positive predictive value, this may provide a faster and more patient-friendly alternative to determine the BRAF mutation status in metastatic melanoma." (PMID 33915880, 2021). "Notably, BRAFi monotherapy may provide profound initial tumor regression in patients with BRAF V600-mutated metastatic melanoma." (PMID 32013263, 2020). "Indeed, a first-in-human clinical trial of Dabrafenib, Trametinib, and Pembrolizumab (NCT02130466) in 15 patients with BRAF-mutated metastatic melanoma found that the combination of BRAF and MEK inhibitors with PD-1 blocking therapy induced an objective responses in 11 patients (73%)." (PMID 33344447, 2020). "Likewise, although cobimetinib is a first-generation MEK inhibitor, its addition to the BRAF inhibitor vemurafenib significantly increases the durable response rate over single-agent BRAF-inhibitor therapy in patients with BRAF V600-mutated metastatic melanoma." (PMID 28474232, 2017). "For example, patients with metastatic colorectal cancer who have KRAS mutations would not be expected to respond to anti-EGFR therapies such as cetuximab, whereas patients with metastatic melanoma who have a BRAF mutation may be suitable for anti-BRAF therapies such as vemurafenib and dabrafenib." (PMID 28114309, 2017). "Ipilimumab, therefore, provides clinical benefit to patients with the BRAFV600 mutation, suggesting that optimal sequencing of ipilimumab and vemurafenib for BRAF-mutated metastatic melanoma should be investigated further as it may be beneficial to use ipilimumab earlier in the disease course." (PMID 24885479, 2014). "Notably, a recent phase III trial showed that treatment with a new MEK inhibitor (GSK1120212, GlaxoSmithKline) determined improved rates of progression-free and overall survival among patients who had metastatic melanoma with mutated BRAF, with very low toxicity." (PMID 24238212, 2013). "High‐dose IL‐2 represents a treatment option in patients with metastatic melanoma after first‐line ICIs‐based immunotherapy and BRAF/MEK‐targeted therapy." (PMID 41492362, 2026). "Initially approved for metastatic melanoma, vemurafenib has shown partial efficacy in BRAF-mutant gliomas in case series and small trials." (PMID 41514664, 2026). "Our patient is a 71-year-old male with BRAF wild-type metastatic melanoma who was diagnosed with a rare irAE after being treated with PD-1 and CTLA-4 immunotherapy." (PMID 40751168, 2025). "Targeted therapy with BRAF and MEK kinase inhibitors (BRAF/MEKi) represents an essential treatment option for metastatic melanoma patients with BRAF mutated disease after progression on immunotherapy." (PMID 41550951, 2025). "BRAF mutant metastatic melanoma is the only setting where we have dedicated randomised trials to assess the sequencing of targeted therapy and ICI." (PMID 40362630, 2025).
metastatic melanoma (continued). "Combining CDK4/6 (palbociclib) and a MEK inhibitor (trametinib) overcame this resistance, offering a promising strategy for patients with metastatic melanoma who are refractory to BRAF/MEK therapy." (PMID 40282469, 2025). "Clinical trials have investigated various combination therapies to improve the effectiveness of BRAF inhibitors in the treatment of metastatic melanoma, such as the combination of MEK inhibitors and immune checkpoint blockade." (PMID 41284701, 2025). "Before novel systemic treatments significantly improved outcomes in metastatic melanoma, a study of 912 patients diagnosed with cutaneous melanoma analyzed the relationships between NRAS and BRAF mutations, tumor characteristics, and survival." (PMID 40332392, 2025). "Following its demonstrated effectiveness against BRAF V600E metastatic melanoma, investigations of combined MEK/BRAF inhibition have been expanded to include glioblastoma variants." (PMID 40725122, 2025). "While there have been advancements in treating metastatic melanoma using BRAF-MEK targeted therapies and immunotherapies, effective treatments remain elusive for patients for whom these therapies have failed." (PMID 40282469, 2025). "Increasing efforts are underway to investigate PARP inhibitors as a viable treatment option for advanced and metastatic melanoma, both as monotherapy and in combination with other agents such as immune checkpoint inhibitors and BRAF/MEK inhibitors." (PMID 40842586, 2025). "A total of 177 patients with BRAF‐mutant metastatic melanoma undergoing BRAF/MEK inhibitor therapy were included." (PMID 40451782, 2025). "Despite these promising findings, the question of how anti-PD-1 monotherapy alone compares to BRAF/MEK inhibition in BRAF-mutant metastatic melanoma remains incompletely resolved." (PMID 40758471, 2025). "In metastatic melanoma, the landmark KEYNOTE-006 trial demonstrated that patients, including those harboring BRAF mutations, benefited from immunotherapy." (PMID 40332392, 2025). "Both animal studies and clinical trials have illustrated that BRAF monotherapy yields a high rate of objective response and enhances overall survival compared to chemotherapy in metastatic melanoma." (PMID 40818129, 2025). "The Food and Drug Administration (FDA) first approved the BRAF inhibitor vemurafenib in 2011 for the treatment of metastatic melanoma, with dabrafenib receiving approval in 2013." (PMID 40332392, 2025). "A range of systemic therapeutic agents is currently available for patients with intestinal metastatic melanoma, including chemotherapy, BRAF-targeted therapies, and immune checkpoint inhibitors." (PMID 39850452, 2025). "Vemurafenib, another BRAF inhibitor for metastatic melanoma, has ocular adverse effects in about 22% of patients." (PMID 41568391, 2025). "This study evaluates the impact of DDIs on clinical outcomes in patients with metastatic melanoma treated with BRAF/MEK inhibitors." (PMID 40451782, 2025). "Atezolizumab, a PD-L1 inhibitor, received FDA approval in 2020 to be used with cobimetinib (MEK inhibitor) and vemurafenib (BRAF inhibitor) in patients diagnosed with BRAF V600 unresectable or metastatic melanoma." (PMID 40004731, 2025). "Our previous studies also found that primary tumor characteristics maintained their prognostic power as independent variables for survival in metastatic melanoma patients treated with immune checkpoint inhibitors or BRAF and MEK inhibitor combinations." (PMID 41008922, 2025). "The potent and selective inhibitors of BRAF‐mutant kinase vemurafenib (V), dabrafenib (D), and encorafenib (E) have demonstrated an advantage in survival outcomes in untreated BRAFv600 mutant metastatic melanoma (MM) compared with standard chemotherapy." (PMID 40451782, 2025).